SPG7 (SPG7 matrix AAA peptidase subunit, paraplegin)
Diseases named in the same sentence as SPG7 in open-access papers (continued):
Sharing a sentence is not in itself a finding about the gene and the disease.
infection (2 papers, 2016 to 2022). The state of being infected such as from the introduction of a foreign agent such as serum, vaccine, antigenic substance or organism. "Further, there was a clear suppression of AMP reporter gene expression in both mutant backgrounds upon spg-7(RNAi) following infection." (PMID 35224461, 2022). "Using a transcriptional reporter strain for AMP expression (nlp-29p::GFP), we also confirmed that spg-7 inactivation resulted in a robust block of AMP expression after infection compared to the sta-1 control clone." (PMID 35224461, 2022). "Inactivation of four of them (ant-1.1, atp-4, spg-7, and ucr-1) abrogated nlp-29 gene expression after infection to the same degree as the positive control, dcar-1, while knocking down gas-1 did not have a statistically significant effect." (PMID 27129311, 2016). "Here, we confirm that RNAi against spg-7 triggers the UPRmt and blocks AMP induction during infection, whereas infection itself does not trigger the UPRmt." (PMID 35224461, 2022). "Here, we first confirmed that knock-down of the mitochondrial metalloprotease spg-7 by RNAi activates the UPRmt through the induction of hsp-6p::GFP reporter, and showed that infection by D. coniospora did not induce this reporter." (PMID 35224461, 2022).
movement disorder (2 papers, 2022 to 2024). Neurological conditions resulting in abnormal voluntary or involuntary movement, which may impact the speed, fluency, quality and ease of movement. "Comparative Genomic Hybridization (CGH)-array and gene testing for mutations in PLA2G6, PANK2 and SPG7 were negative, as well as NGS-based panel screening of 102 genes associated with movement disorders in childhood." (PMID 39063023, 2024).
SPG7 also shares sentences with these, for which no sentence is quoted: cerebellar ataxia (18 papers); episodic ataxia (4); ataxia telangiectasia (3); epilepsy (3); myopathy (3); tumor (3); Autosomal recessive spastic ataxia of Charlevoix-Saguenay (2); Encephalopathy (2); Friedreich ataxia (2); hereditary ataxia (2); neurodevelopmental disorder (2); Spastic paraparesis (2); abetalipoproteinemia (1); adrenomyeloneuropathy (1); amyotrophy (1); Atrioventricular canal defect (1); autonomic dysfunction (1); autosomal recessive spastic ataxia (1); axonal sensory neuropathy (1); breast tumour (1); butyrylcholinesterase deficiency (1); cardiac hypertrophy (1); cataract (1); cerebellar disorder (1); cerebrotendinous xanthomatosis (1); dilated cardiomyopathy (1); Early-onset spastic ataxia-neuropathy syndrome (1); Ehlers-Danlos syndrome (1); episodic ataxia type 2 (1); fragile X-associated tremor/ataxia syndrome (1).
A further 35 diseases each share a sentence with SPG7 in 1 paper.